FOXA1 (forkhead box A1)
Diseases named in the same sentence as FOXA1 in open-access papers (continued):
Sharing a sentence is not in itself a finding about the gene and the disease.
prostate carcinoma (continued). "We present an optimized protocol to enhance the transcription factor profiling in human tumor tissue and successfully performed ChIP-seq for ERα, AR, and FOXA1 in primary breast, endometrium, and prostate cancer specimens." (PMID 30620009, 2019). "Gene fusions involving E26 transformation-specific (ETS) family members and coding mutations mainly affecting speckle-type POZ protein (SPOP), forkhead box protein A1 (FOXA1), and isocitrate dehydrogenase 1 (IDH1) are found in primary prostate cancer." (PMID 31200487, 2019). "We found that FOXA1 is the TF motif most frequently enriched at enhancers in prostate cancer-specific enhancer–promoter loops." (PMID 31515496, 2019). "For example, we show that FOXA1 is enriched in prostate cancer-specific enhancer-promoter loop anchors." (PMID 31515496, 2019). "The large majority of FOXA1 mutants observed in prostate cancers promote a pronounced luminal differentiation program, whereas R219 mutants block luminal differentiation and promote a mesenchymal and neuroendocrine transcriptional program." (PMID 31366128, 2019). "In the colon cfDNA pool, TFs EVX2, DLX2, HNF1A, HNF4A, and HNF4G and TFs AR and HOXB13 in the prostate cancer cfDNA pool had increased accessibilities, whereas FOXA1 exceeded the >5 z-score threshold in both the prostate and breast pool." (PMID 31604930, 2019). "Among these factors, GATA2 and FoxA1 play particularly essential roles in androgen receptor signaling in prostate cancer cells." (PMID 31552182, 2019). "FOXA1 is an important TF in breast and prostate cancers and is known to be a target of both MAPK and AKT." (PMID 30994899, 2019). "AL121790.1 is in head-on orientation with FOXA1, and its RNA products overlap with the FOXA1 3′-UTR in prostate cancer cells." (PMID 30272002, 2018). "In prostate cancer, the androgen receptor decreases the expression of miR-29b which targets both TET2 and 5-hmC; 5-hmC represses FOXA1 activity, while its reduction activates the mTOR pathway and AR of prostate cancer." (PMID 29850477, 2018). "FOXA1 is an AR transcription factor that promotes prostatic cancer oncogenesis and progression mainly by increasing the transcriptional activity of AR." (PMID 29581876, 2018). "A previous study found that CREB1 and FoxA1 associated with advanced prostate cancer, and CREB1/FoxA1 target gene panels can predict prostate cancer recurrence." (PMID 30138363, 2018). "We applied transIndel to large-scale prostate cancer DNA-seq and RNA-seq data sets and reported novel recurrent FOXA1 indels and exitron splicing events." (PMID 29673323, 2018). "Forkhead box A1 (FOXA1) belongs to the forkhead class transcription factor family, playing pioneering function for hormone receptors in breast and prostate cancers, and mediating activation of linage specific enhancers." (PMID 30572598, 2018). "To further test the TF enrichment, we carried out ChIP assays, followed by quantitative PCR and confirmed the chromatin binding of prostate cancer master regulators AR, FOXA1, and HOXB13 at the SNP site." (PMID 29789573, 2018). "Similar results were recently obtained in prostate cancer, in which it has been demonstrated that FOXA1 expression is closely related to prognosis independently of AR level." (PMID 29970021, 2018). "The up-regulation of FOXA1 is highly correlated with the malignancy of lung cancer, prostate cancer, and esophageal cancer." (PMID 30360388, 2018). "Until now, studies on the role of FOXA1 in carcinogenesis have focused mainly on breast and prostate cancers." (PMID 29208003, 2017). "Targeting the pioneer factor FOXA1 showed contradictory results for AR activity and prostate cancer prognosis." (PMID 28264478, 2017).
prostate carcinoma (continued). "We therefore asked if H2A.Zac nucleosomes that flank AR-enhancers are associated with any of the AR co-factors with a known oncogenic role in prostate cancer, including CtBP131, CtBP232, FOXA-1, and GATA-233." (PMID 29116202, 2017). "In prostate cancer, FOXA1 carries reverse prognostic implications with high expression associated with hormone therapy resistance." (PMID 26797644, 2016). "In prostate cancer cell lines, FOXA1 is required for androgen receptor activation, and over-expression of FOXA1 increases AR binding throughout the genome." (PMID 26986977, 2016). "In the human adult prostate, FOXA1 is expressed in the epithelial cells of the peripheral zone, the site from which the majority of prostate cancers originate." (PMID 26986977, 2016). "The aim of this study was to evaluate the association between FOXA1 staining level and BCR after SRT for recurrent prostate cancer." (PMID 26986977, 2016). "While numerous studies have emphasized the importance of FOXA1 in primary prostate cancer growth, its role in metastatic disease is yet to be fully defined." (PMID 26986977, 2016). "It has been established that AR transactivation of target genes in cultured prostate cancer cells requires pioneer factors, such as FoxA1 and GATA2." (PMID 27374105, 2016). "The forkhead transcription factor FOXA1 is emerging as a critical player in prostate cancer biology." (PMID 26986977, 2016). "This is the first study to date that assesses the ability of FOXA1 staining levels in primary prostate cancer tumors to predict BCR among men undergoing SRT." (PMID 26986977, 2016). "Results from clinical studies have indicated that high levels of FOXA1 have been associated with an increased risk of BCR and prostate cancer-specific death after RP." (PMID 26986977, 2016). "A strong overlap of the identified eight FAIRE-seq peaks was found with known players in prostate cancer including AR, FOXA1, ERG, bromodomains BRD2 and BRD3 and, interestingly, MYC." (PMID 26412853, 2015). "KLF4 and another epithelial determinant, FoxA1, are direct transcriptional inhibitors of Slug expression in mouse and human prostate cancer cells." (PMID 25879941, 2015). "Previous studies have indicated that epigenetic markers and collaborating transcription factors can be ascribed to androgen-independent prostate cancer, including histone markers, FoxA1, MED1(Mediator complex subunit 1) and FOXO1." (PMID 25481872, 2015). "In prostate cancer biopsies, immunohistochemistry staining revealed a co-localization of MB with AR and FOXA1." (PMID 26559958, 2015). "Change in FOXA1 expression in prostate cancer therefore seems to lead to reprogramming of AR binding events." (PMID 24849812, 2014). "FOXA1 also binds directly to AR and regulates transcription of prostate-specific genes in prostate cancer." (PMID 24512546, 2014). "In acute myelocytic leukemia, esophageal squamous cell carcinomas, lung adenocarcinomas, thyroid carcinoma, prostate cancer, and AR-positive molecular apocrine breast cancer, FOXA1 acts as an oncogene." (PMID 24512546, 2014). "Recent global gene expression studies of prostate cancer and triple-negative breast cancer have shown that high FOXA1 expression, which correlates positively with AR level, promotes tumor proliferation." (PMID 24512546, 2014). "In prostate cancer FOXA1 has been found to be a pioneer factor for AR for some binding events, but also a repressor." (PMID 24849812, 2014). "For both promoters and enhancers we also identified a subset of disruptive variants that target response elements for factors of special interest to prostate cancer, namely AR, FOXA1, NKX3-1, TCF7L2, MYC, GATA1 and GATA3." (PMID 24497837, 2014). "In prostate cancer cells and in normal mouse prostate, AR binding is primed by FoxA1, and a distinct cis-element, composed of an ARE half-site and a FoxA1 element, is highly enriched among the AR-binding sequences." (PMID 24459135, 2014).
prostate carcinoma (continued). "Recently, forkhead box protein A1 (FOXA1) has been shown to play an important role as AR co-regulator in prostate cancer." (PMID 23896594, 2013). "In prostate cancer, FOXA1 genomic locus amplification was only observed in metastatic samples, which correlates with the observation of elevated FOXA1 staining in metastases and high grade tumors." (PMID 23420418, 2013). "FOXA1 primarily an enhancer pioneer transcription factor and acts as a global mediator of steroid receptor action in hormone-dependent cancers including prostate cancer." (PMID 23896594, 2013). "If AR driven prostate cancers readily acquire ligand independence, elevated FOXA1-AR activity would be an advantage to the tumor, supporting the observation that high FOXA1 is a marker of poor patient outcome." (PMID 23420418, 2013). "It was reported FOXA1 gene was amplified and overexpressed in metastatic prostate cancers and particularly in CRPC cases." (PMID 23896594, 2013). "Increased levels of WT FOXA1 significantly increase prostate cancer proliferation and the size of xenograft tumors, possibly due to increased AR-mediated growth." (PMID 23420418, 2013). "FOXA1 amplification in prostate cancer was identified from the profiling of eight systemic metastatic tumors in a range of organs from six unrelated patients." (PMID 23420418, 2013). "In prostate cancer, however, when FOXA1 is lost, AR can still bind to chromatin and in fact occupies new binding sites which are coupled to changes in its' transcriptional targets." (PMID 23420418, 2013). "A protein commonly expressed in hormonally-driven cancers is the transcription factor FOXA1 which appears to be intrinsic to tumor development in both breast and prostate cancer." (PMID 23420418, 2013). "We assessed the role of FOXA1 on androgen-independent prostate cancer using C4-2 cells, established from castrated host of LNCaP cells." (PMID 22879989, 2012). "Increased FOXA1 expression has also been observed in colon, lung, thyroid, esophageal cancer and prostate cancer." (PMID 22879989, 2012). "Depletion of FOXA1 in a prostate cancer cell line (LNCaP) using small interfering RNA (siRNA) significantly inhibited AR activity, led to cell-growth suppression, and induced G0/G1 arrest." (PMID 22879989, 2012). "Moreover, FOXA1 has been identified as an important regulator of alternative splicing in prostate cancer." (PMID 40356745, 2025). "Strikingly, overall FOXA1 alterations were present in 25.4% of AP patients with prostate cancer." (PMID 39745364, 2025). "In prostate cancer, FOXA1 contributes to AR signaling even in low androgen environments." (PMID 41124032, 2025). "In addition to common essential genes, genes with known relevance to prostate carcinoma pathobiology, including AR, FOXA1, HOXB13, GATA2, SPOP, and AKT, were depleted." (PMID 40956611, 2025). "Moreover, it lays the groundwork for further research into the therapeutic potential of targeting FOXA1 to improve drug efficacy in prostate cancer." (PMID 39858458, 2025). "It highlights the potential use of SNP rs9364554 as a biomarker to predict drug efficacy in precisely treating prostate cancer patients and lays the groundwork for further exploration into the therapeutic potential of targeting FOXA1 to improve drug efficacy in prostate cancer." (PMID 39858458, 2025). "Furthermore, studies have indicated that in the case of prostate cancer, JQ1 can enhance the invasion of tumors by suppressing FOXA1, a protein that inhibits invasion in prostate cancer." (PMID 39838405, 2025).
prostate carcinoma (continued). "Immunoprecipitation of endogenous HIF1α pulled down FOXA1, while reciprocal immunoprecipitation of FOXA1 confirmed specific co-precipitation of HIF1α, demonstrating bidirectional interaction in prostate cancer cells." (PMID 40643528, 2025). "Looking specifically at AR-associated gene expression in our treatment-naïve primary prostate cancer samples, our AIPC cohort demonstrates significantly lower expression of AR, FOXA1, TMPRSS2, KLK3, AZGP1, and several other AR-associated genes when compared with the non-AIPC cohort." (PMID 39859392, 2025). "Our findings underscore the key role of FOXA1 in prostate cancer progression and treatment resistance by regulating SEMA3C expression and suggest that SEMA3C may be a driver of growth and tumor vulnerability of mCRPC harboring FOXA1 alterations." (PMID 38528115, 2024). "FOXA1 has been well studied in various stages of prostate cancer." (PMID 39470735, 2024). "A previous study reported that FoxA1 could modulated by SUMOylation during functional interplay with androgen receptor in prostate cancer cells." (PMID 39277582, 2024). "Our work adds to the body of knowledge amassing around FOXA1 in prostate cancer." (PMID 38528115, 2024). "In prostate cancer cells, similar interactions between AR and STAT5a/b signaling were shown and in hepatocellular cancer, CBG expression is regulated via the pioneer factors FOXA1 and the estrogen receptor, potentially underlying sex differences in CBG." (PMID 39240718, 2024). "Overall, our data suggest that the FOXA1/PUS1/EIF3b signaling axis may serve as an effective therapeutic target for treating prostate cancer bone metastasis." (PMID 39247811, 2024). "In addition to its transcriptional pioneering function, FOXA1 was recently shown to inhibit interferon signaling in breast and prostate cancer models." (PMID 39622796, 2024). "In another study, Sjöstrom and colleagues (2022) saw that local 5hmC enrichment at enhancers or upstream of transcription start sites of prostate cancer drivers, most notably androgen receptor (AR) and forkhead box protein A1 (FOXA1), correlated with their gene expression." (PMID 39336751, 2024). "Additionally, the decreased expression of FOXA1 in prostate cancer led to an increase in immunosuppressive macrophage infiltration, which is dependent on HIF-1α expression." (PMID 38287425, 2024). "Our findings highlight the FOXA1/PUS1/EIF3b axis as a critical mediator of prostate cancer bone metastasis and suggest that targeting this pathway could be a promising therapeutic strategy." (PMID 39247811, 2024). "In LnCAP prostate cancer cells, FOXA1 and GATA2 independently bind to the ABCC4 gene and recruit chromatin loop-forming factors such as MED1 from distal sites to the cluster two region, allowing androgen receptors to bind and promote transcription upon hormone stimulation." (PMID 39114357, 2024). "To address this gap, we identified semaphorin 3C (SEMA3C) as a candidate FOXA1 target gene that might mediate the pro-oncogenic effects such as increased proliferation and EMT linked with FOXA1 variants in prostate cancer." (PMID 38528115, 2024). "Both SKO and DKO samples exhibited enrichment of H3K27ac at the SE region of Foxa1 in line with previous publications, which demonstrates that FOXA1 drives prostate cancer initiation and progression and plays an important role in prostate cancer phenotypic plasticity." (PMID 39113611, 2024). "In FOXA1 mutant prostate cancer, 9 of the upregulated genes were oncogenes/driver genes, while 45 of the downregulated genes were tumor suppressor genes specifically related to prostate cancer." (PMID 37958805, 2023). "Among them, FOXA1 was wildly regarded as pioneer transcription factor (pTF) in prostate cancers." (PMID 37876590, 2023).
prostate carcinoma (continued). "The molecular landscape of prostate cancer is characterized by recurrent genomic alterations, including the fusion of ETS family genes such as ERG, ETV1, ETV4, or FLI1, and genetic mutations involving SPOP, FOXA1, or IDH1." (PMID 37958805, 2023). "Therefore, tumor expression of FOXA1 in ER+ breast and AR+ prostate cancers is often a predictive indicator of sensitivity to nuclear hormone receptor–targeted therapies." (PMID 37691854, 2023). "The FOXA1 pioneer factor is an essential mediator of steroid receptor function in multiple hormone-dependent cancers, including breast and prostate cancers, enabling nuclear receptors such as estrogen receptor (ER) and androgen receptor (AR) to activate lineage-specific growth programs." (PMID 37691854, 2023). "Interestingly, regulatory T cell recruiting in Step 4 of the cancer–immunity cycle was lower in FOXA1 mutant prostate cancer compared to the control group." (PMID 37958805, 2023). "Considering the difficulties of drug development for transcription factor due to its structural disorder and involvement in various pathways, we have taken a different approach to identify a candidate therapeutic target for FOXA1 mutant prostate cancer using its own molecular characteristics." (PMID 37958805, 2023). "Notably, a substantial proportion of prostate cancers, up to 74%, can be attributed to fusions found in ETS-family genes (ERG, ETV1, ETV4, and FLI1) or mutations in genes such as SPOP, FOXA1, or IDH1." (PMID 38067216, 2023). "Considering previous studies and our results, we suggest that MAOA inhibitors might have a special efficacy on FOXA1 mutant prostate cancer compared to the control group." (PMID 37958805, 2023). "Considering previous studies highlighting the importance of CXCL13 axis in B cell recruitment and our finding of CXCL13 downregulation in FOXA1 mutant prostate cancer, it is plausible to suggest that CXCL13 may be a contributing factor to these results." (PMID 37958805, 2023). "The overexpression of FOXA1 may play a key role in prostate cancer immune coldness by regulating IFN-responsive gene expression." (PMID 35892678, 2022). "FOXA1 has been identified as a promoter of prostate cancer pathogenesis and progression." (PMID 35892678, 2022). "Importantly, therapeutic strategies targeting the link between FOXA1 and the AR would be relevant in disease stages where AR signaling continues to be critical and where FOXA1 expression remains high, such as primary prostate cancer and CRPC." (PMID 36212399, 2022). "Comparing PCa AR-cistrome to fibroblast AR-cistrome, the degree of overlap between the two cell types is greatly increased when FOXA1 is silenced in the epithelial prostate cancer cells, which suggests a role for FOXA1 in determining phenotypically epithelial specificity of AR signalling." (PMID 37435460, 2022). "Interestingly, FOXA1 was shown to induce TET1 expression through direct binding to its cis-regulatory elements, which in turn led to binding of TET1 to FOXA1 sites mediating local DNA demethylation in prostate cancer cells." (PMID 35331302, 2022). "It is of interest that this converged dimerization coincides with the predicted FOXA1 homodimer model in the prostate cancer cell, LNCaP, suggesting that the converged binding might be related to biological roles of FOXA1 in cancer cells." (PMID 35920317, 2022). "FOXA1 is highly expressed in prostate cancer cells and prostate adenocarcinoma (PRAD)." (PMID 36292640, 2022). "Next, we explored how ivermectin inhibited FOXA1 expression in prostate cancer." (PMID 36050295, 2022). "Together, we found TBX3 and NFIC were nuclear proteins associated with CREB5, FOXA1, and functionally impacted prostate cancer cell viability and ART resistance even absent of CREB5." (PMID 35550030, 2022). "Notably, AR+FOXA1+ prostate cancer cells were more sensitive to these inhibitors than SMARCA4-null cancer cell lines." (PMID 34937944, 2022).